CRP (C-reactive protein)
Diseases named in the same sentence as CRP in open-access papers (continued):
Sharing a sentence is not in itself a finding about the gene and the disease.
COVID-19 (continued). "Progranulin showed high discriminative power to differentiate bacterial CAP from COVID-19 (sensitivity 0.91, specificity 0.94, AUC 0.91 (CI = 0.8–1.0) and performed significantly better than PCT, IL-6 and CRP." (PMID 34476621, 2021). "Variations in the hematological indices, renal function, LFTs, as well as derangements of biomarkers like NLR, CRP, LDH, D-dimer, and ferritin, are potent indicators of COVID-19 severity and mortality." (PMID 34084685, 2021). "The serum levels of CRP, troponin-I, ALP, ALT, serum creatinine, and ferritin are markedly increased in COVID-19 patients." (PMID 33628256, 2021). "Many parameters, including convalescent plasma therapy, age, BMI, ALT, HDL, BUN, CRP, Ferritin, NLR, 4C-score and SOFA score were studied for their correlation to mortality in the all severity COVID-19 patients’ groups." (PMID 34822419, 2021). "Elevated C-reactive protein (CRP) and ferritin (FER) have been proposed as biomarkers to monitor the clinical course and determine treatment selection for patients with COVID-19." (PMID 34945095, 2021). "The results of the present study showed that severe COVID-19 patients had serum AAT levels mostly in the normal range at the time of admission, despite high baseline levels of CRP and ESR." (PMID 34007243, 2021). "The longitudinal investigation of these patients showed that inflammatory markers (ESR, CRP) and FIB-4 were higher in the acute COVID-19 than in the post-COVID period." (PMID 34635073, 2021). "Contrary to COVID-19 patients with increased ALT activity, COVID-19 patients with higher GGT activity had significantly higher concentrations of APPs, such as CRP or ferritin, and higher D-dimers levels." (PMID 34680053, 2021). "In parallel to our findings, previous studies have also reported a similar elevation of CRP, D-dimers, LDH, ESR, ferritin, and PCT levels among severe COVID-19 patients admitted to the ICU." (PMID 34084685, 2021). "It is also found that NRS score is positively correlated with CRP and PCT levels, WBC count, and mortality rate of COVID-19, but positively with lymphocyte count." (PMID 33832097, 2021). "Thus, levels of serum CRP may be a predictor for the clinical outcomes of COVID-19 patients." (PMID 33907513, 2021). "Similar features were found when compared the median values of inflammatory (CRP and neutrophils) and liver (FIB-4) markers in COVID-19 patients." (PMID 34300279, 2021). "Changes in the gut microbiome of COVID-19 and H1N1 were correlated with clinical indicators, including WBC, CRP, PCT, D-dimer, IL-2, IL-4, IL-6, and TNF-α." (PMID 35004750, 2021). "The degree of inflammation, as measured by CRP, was significantly greater in MIS-C compared with pediatric COVID-19, as described in other studies." (PMID 33841438, 2021). "Recent reports of COVID-19 suggest significant upregulation in the levels of ESR and CRP post infection." (PMID 34181704, 2021). "In the multivariate model mutually adjusted for CRP, Shannon’s diversity index, age, and antibiotic therapy 6 months prior to COVID-19 diagnosis, the variable CRP and Shannon’s diversity index were significantly associated with COVID-19 severity, while gender was no longer significantly associated." (PMID 34349747, 2021). "Plasma levels of C-reactive protein (CRP), induced by Severe Acute Respiratory Syndrome Coronavirus-2 (SARS-CoV-2) triggering COVID-19, can rise surprisingly high." (PMID 34408751, 2021). "Unselected cohort of 224 COVID-19 patients admitted to hospital that underwent daily PCT and CRP measurements as standard care." (PMID 34859223, 2021). "We present to you the CAPA score calculated from CRP, age, platelet count, albumin levels, which is an effective score in predicting mortality and ICU admission in COVID-19." (PMID 34784756, 2021). "Several studies have reported that inflammatory markers such as C-reactive protein (CRP), ferritin, interleukin (IL)-6, IL-10, and tumor necrosis factor-α (TNF-α) were significantly elevated in severe COVID-19 cases." (PMID 34408744, 2021).
COVID-19 (continued). "The analysis results showed that the serum Ca2+ of COVID-19 patients was significantly negatively correlated with PCT, calcitonin, D-dimer, PFDP, ESR, CRP, and IL-6." (PMID 34222271, 2021). "The inflammatory markers C-reactive protein (CRP), serum ferritin, LDH, D-dimer, IL-6 and IL-2 in severe COVID-19 patients are significantly increased leading to a “cytokine storm”." (PMID 34108015, 2021). "We statistically examined four of these tests that are more important for five COVID-19 patients of our study, including LDH, CRP, lymph count, and ferritin, among which ferritin showed a significant decrease." (PMID 34271988, 2021). "In summary, this study reports the identification of powerful combination of five features [neutrophils (%), hs-CRP, age, lymphocyte (%), and LDH] that helps in accurately predicting the mortality of COVID-19 patients." (PMID 34055710, 2021). "A significant correlation exists between well-controlled blood glucose and lower serum levels of inflammatory markers such as IL-6, high sensitivity c-reactive protein (CRP), and lactate dehydrogenase in COVID-19 patients." (PMID 35095801, 2021). "Lymphopenia is generally seen in COVID-19 and MIS-C and there was higher CRP and ferritin levels also in COVID-19." (PMID 34055688, 2021). "Compared with the non-COVID-19 group, patients with COVID-19 had lower lymphocyte count and eGFR and higher ALT, AST, CRP, and LDH." (PMID 34691316, 2021). "Biomarkers such as CRP and PCT suggested excessive inflammatory stress in vivo and the severe or critical illness of COVID-19 patients." (PMID 34712742, 2021). "These laboratory parameters indicated that innate immune response gets activated during COVID-19 as indicated by markedly raised neutrophil to lymphocyte ratio (NLR) and CRP." (PMID 34760713, 2021). "With this study, we present to you the CAPA score calculated from CRP, age, platelet count, albumin levels as an effective score in predicting mortality and ICU admission in COVID-19." (PMID 34784756, 2021). "The test has high throughput and can perform simultaneous clinical tests for other biomarkers, such as C-reactive protein (CRP), which should also be tracked in COVID-19 suspects." (PMID 32944809, 2021). "Erythrocyte sedimentation rate (ESR), C-reactive protein (CRP), D-dimer showed higher values in COVID-19 survivors (P< 0.001)." (PMID 34777873, 2021). "In the acute COVID-19 group, the medians of LDH, CRP, ferritin, IL-6, and ESR at admission to the hospital were higher than the upper limit of a reference interval." (PMID 34635073, 2021). "Recent studies on COVID-19 laboratory data showed an increase in serum levels of lactate dehydrogenase (LDH), C-reactive protein (CRP), and hepatic enzymes, with a marked decrease in lymphocytes." (PMID 34721903, 2021). "C-reactive protein (CRP), which is frequently high in COVID-19, is a simple biomarker for the inflammatory state." (PMID 34769350, 2021). "Even if CRP and PCT are also elevated in systemic response to COVID-19, the cut-off values in our study are much higher than described to discriminate between mild and severe disease." (PMID 34021897, 2021). "Both adults and children with severe COVID-19 show consistent trends toward elevated lactate dehydrogenase (LDH), C-reactive protein (CRP), procalcitonin (PCT), and D-dimer levels." (PMID 34367265, 2021). "A retrospective cohort study including 288 confirmed COVID-19 patients also demonstrated that CVD with older and higher levels of troponin I (TnI), CRP, and creatinine were more prone to develop into severe or critically severe cases." (PMID 34447386, 2021). "COVID-19 patients with ARDS presented with lymphopenia, increased thrombotic activity, increased CRP, LDH, and ferritin levels." (PMID 33861750, 2021). "The mean C-reactive protein (CRP) level, leukocyte count, and procalcitonin (PCT) level on admission were higher in severe COVID-19 patients than in moderate cases." (PMID 33140176, 2021).
COVID-19 (continued). "C-reactive protein (CRP), a routinely measured inflammatory marker, was increased in most patients with COVID-19." (PMID 34185186, 2021). "After evaluating 189 patients, they showed that age, RDW, BUN, CRP, LDH, ALB and DBIL were predictive factors for severe COVID-19." (PMID 34254030, 2021). "Higher Acute Physiology and Chronic Health Evaluation II (APACHE II) scores, monocyte counts, and CRP and ALT levels were found in male COVID-19 patients." (PMID 33350432, 2021). "Pointing to proinflammatory and insulin impairing the action of fetuin-A, its levels were significantly lower in COVID-19 patients despite higher HOMA-IR, CRP, and ferritin levels." (PMID 34680053, 2021). "CRP, D-dimer, and IL-6 are commonly elevated and LYM% diminished in patients with COVID-19 and correlate with disease severity in previous studies." (PMID 33902676, 2021). "The most frequently reported laboratory findings in children with COVID-19 are white blood cell and platelet count, erythrocyte sedimentation rate (ERS), C-reactive protein (CRP), urea, creatinine, alanine aminotransferase, and aspartate aminotransferase." (PMID 34123972, 2021). "However, further binary logistic regression analysis revealed that CRP could not be used as a risk factor related to the severity and risk of death of diabetic patients with COVID-19, although the OR value was relatively high." (PMID 34164413, 2021). "Other studies have reported an elevation in acute-phase reactants among patients with COVID-19, including ESR, C-reactive protein (CRP), serum amyloid A, and ferritin—suggesting a rapid activation of the innate immune response." (PMID 33693030, 2021). "The group of COVID-19 patients with higher total and LDL-cholesterol levels was characterized by significantly lower CRP and IL-6 serum concentrations and significantly elevated PLT count and iron level." (PMID 34680053, 2021). "Amidst patients with poor outcome, leucocyte count, D-dimers, C-reactive protein, procalcitonin, troponin I, NT-pro-BNP, CK, AST, and LDH levels were significantly higher when compared to COVID-19 patients with a more favorable course of disease." (PMID 34150860, 2021). "Significantly elevated concentrations of C-reactive protein (CRP) produced as a result of macrophage stimulation by IL-1β, IL-6, or TNF-α have also been observed in COVID-19 patients." (PMID 33466589, 2021). "Multiple general linear regressions of innate immune cells, c-reactive protein, fibronogen, ALT and AST in patients with COVID-19." (PMID 33770147, 2021). "While CRP may not show complete concordance with clinical outcomes, we argue that if dysregulated inflammation is indeed a key pathogenic driver in severe COVID-19, an immunomodulating drug capable of ameliorating those outcomes is also likely to show early improvement of CRP." (PMID 34764169, 2021). "In multivariable COX proportional hazard analysis, high levels of CRP, hs-cTnT, and LDH as well as low blood oxygen saturation, and older age were identified as the strongest predictors of poor outcome in COVID-19." (PMID 34204453, 2021). "Lab findings showed that she had elevated inflammatory markers including CRP of 87 mg/dL, D-dimer 917 ng/mL, Ferritin of 1245 ng/mL, and LDH of 598 U/L and a positive COVID-19 PCR." (PMID 34512966, 2021). "A significant rise in C-reactive protein (CRP), aspartate aminotransferase (AST), procalcitonin, lactate dehydrogenase (LDH), IL-6 and ferritin was seen in the COVID-19 patients, indicative of the ongoing inflammatory response and tissue damage." (PMID 34344929, 2021). "It is well known that C-reactive protein (CRP) is the acute-phase protein and the active regulator of host innate immunity, which is highly predictive of the need for mechanical ventilation and may guide escalation of treatment of COVID-19-related uncontrolled inflammation." (PMID 34447386, 2021).
COVID-19 (continued). "We found significantly higher levels of CRP, fibrinogen, ferritin, D-dimer and CPK, and significantly lower albumin levels and total serum protein in MIS-C compared to children with COVID-19." (PMID 34576853, 2021). "Conventional parameters routinely used to define COVID-19 severity, including NLR, CRP and LDH, and creatinine were also different between survivors and non-survivors or patients transferred or not to ICU." (PMID 34663207, 2021). "Patients with COVID-19 being treated with BBs also showed the highest numbers of some inflammatory markers such as NLR, CRP, and SCr in the second evaluation." (PMID 34912542, 2021). "The patients who recovered from COVID-19 had significantly lower plasma levels of KYN, CRP, IL-6, ferritin, NTproBNP, cTnT, and creatinin." (PMID 34943063, 2021). "Furthermore, studies suggest that the pathophysiology of COVID-19-related AKI is similar to that of sepsis-associated AKI, as the majority of damage within the kidneys is due to the hemodynamic and immunologic effects of the infection, as supported by the increased levels of CRP and Il-6." (PMID 34209289, 2021). "The results showed that hospitalized patients with COVID-19 had low serum levels of AAT and high CRP levels at the first days of hospitalization." (PMID 34007243, 2021). "Generally, patients with COVID-19 had elevated lactate dehydrogenase (LDH) and CRP, which indicates organ damage and inflammation." (PMID 34829418, 2021). "Lastly, we propose a specific cutoff value of a ratio consisting of systemic CRP and TCC as well as CXR score as a discriminating factor of survivability in COVID-19 patients." (PMID 34960645, 2021). "Elevated CRP, PCT, and ferritin markers of inflammation were obtained in patients with COVID-19, when compared to the healthy controls." (PMID 33306332, 2021). "In the present work, we aim to clarify the characteristics and clinical significance of peripheral blood cell counts (BCCs) and the levels of CRP, AST, ALT, and APACHE II scores in male and female COVID-19 patients." (PMID 33350432, 2021). "Investigations revealed elevated CRP (158 mg/L), persistent detection of SARS-CoV-2 and radiographic changes consistent with COVID-19 pneumonitis." (PMID 34969393, 2021). "Observational studies have reported that elevated inflammatory biomarkers such as C-reactive protein (CRP), IL-6, and ferritin were related to higher incidences of myocardial injury in COVID-19 patients." (PMID 34677197, 2021). "Many coagulation indices, including APTT, PT, TT, FIB, and INR, and some other hematologic indices, including leukocyte, CRP, and D-dimer on admission, were shown to be different between the survivors and non-survivors and could be used as prognostic indicators for a fatal outcome of COVID-19." (PMID 34164443, 2021). "Such a model recently identified CRP, LDH, and urea as significant prognostic factors for severe COVID-19 illness." (PMID 34621457, 2021). "have used the HNC-LL score that considered hypertension, neutrophil count, C-reactive protein (CRP), lymphocyte count, and lactate dehydrogenase (LDH) to predict the severity of COVID-19 with AUC higher than 0.82 based on 442 patients." (PMID 34541519, 2021). "Six features, including disease severity, age, levels of high-sensitivity C-reactive protein (hs-CRP), lactate dehydrogenase (LDH), ferritin, and interleukin-10 (IL-10), were selected as predictors for COVID-19 mortality." (PMID 33410720, 2021). "Clinical features and laboratory parameters such as neutrophil-to-lymphocyte ratio (NTL), C-reactive protein (CRP), creatinine, urea, and lactate dehydrogenase (LDH) are used as indicators of COVID-19 severity." (PMID 34685377, 2021). "Our results demonstrated that the initial CT scores and the worst CT scores were significantly correlated with both CRP and LDH levels, which is consistent with prior reports in COVID-19 and SARS 12, 19-24." (PMID 33526989, 2021).
COVID-19 (continued). "The patients at KCH also had higher levels of CRP, creatinine, LDH, and possibly a lower number of lymphocytes than the OUH patients; all of which are known predictors for severe COVID-19." (PMID 34432797, 2021). "Retrospective analysis of 191 COVID-19 patients in China revealed increased serum inflammatory markers, including TNF-α, C-reactive protein (CRP), ferritin, D-dimer, and IL-6, and cardiac damage markers, including troponin T." (PMID 34061779, 2021). "A comparison between healthy plasma and acute COVID-19 solubilized clots also showed a significant increase in coagulation factor XIII A chain, VWF Complement component C7 and CRP." (PMID 34328172, 2021). "Some of these parameters, including the PaO2:FiO2 ratio, leukocyte counts and D-dimer, C-reactive protein (CRP) and creatinine concentrations, among others, have been previously reported as mortality predictors in ventilated and/or ICU COVID-19 patients." (PMID 35186962, 2021). "The decrease in CRP and D-dimer suggests a possible protective effect related to ACEi/ARB use in COVID-19, however, more studies with larger sample sizes are needed to establish this effect." (PMID 33728141, 2021). "Increased levels of C-reactive protein (CRP), D-dimer, fibrinogen, procalcitonin, lactate dehydrogenase (LDH), and ferritin have also been reported in severe COVID-19 patients." (PMID 34439920, 2021). "Fourth, CRP, blood oxygen saturation, LDH, hs-cTnT, and age were strong predictors of poor outcome in COVID-19." (PMID 34204453, 2021). "Inflammatory markers, such as C reactive protein (CRP), procalcitonin (PCT), and ferritin, were markedly elevated in critically ill COVID-19 patients." (PMID 33602326, 2021). "We have also not been able to report on antimicrobial use and microbiology results, which would give important insight into the usefulness of using CRP and PCT levels as aids for antimicrobial stewardship on the ICU in patients with COVID-19." (PMID 34362074, 2021). "Univariate analyses in our study confirm the findings in the Chinese ARDS patients study, showing higher body temperature in patients with influenza and higher levels of CRP, LDH and AST in patients with COVID-19." (PMID 33274416, 2021). "Nevertheless, the abdominal infection causing acute abdomen resulted in more abnormal laboratory test results, such as CRP, PCT, WBC, neutrophils, and fibrinogen, in infectious acute abdomen patients than in COVID-19 patients (p < 0.001)." (PMID 33996842, 2021). "The lymphopenia and increased CRP, ALT, D-dimer, ferritin, and LDH were observed in patients with ARDS-COVID-19." (PMID 33861750, 2021). "Although possible biological relationships exist between the biomarkers (hs-CRP, LDH, serum ferritin, and IL-10) and severity of COVID-19, the effects of these biomarkers in COVID-19 pathogenesis still need validations and further in-depth investigations." (PMID 33410720, 2021). "We found CRP to be an independent predictor for an antibiotic prescription for RTI in suspected and proven COVID-19." (PMID 34223137, 2021). "Correlation of both NLR and PLR with already established inflammatory markers such as CRP, ESR, and those specific for COVID-19 (ferritin, D-dimers, and eosinophils) were also evaluated." (PMID 34181675, 2021). "We found that most COVID-19 patients had elevated ESR rates, and over 40% of the patients presented increased CRP and D-dimer levels." (PMID 33914805, 2021). "Patients with severe and critical COVID-19 were characterized by higher levels of IL6, C-reactive protein and soluble IL2-receptor expression." (PMID 34869058, 2021). "This study aimed to evaluate the association and temporal trends of D-dimer and C-reactive protein (CRP) levels with the incidence of venous thromboembolism (VTE), hospital mortality, and costs among inpatients with COVID-19." (PMID 34909913, 2021).